ST3GAL4 (ST3 beta-galactoside alpha-2,3-sialyltransferase 4)
Diseases named in the same sentence as ST3GAL4 in open-access papers (continued):
Sharing a sentence is not in itself a finding about the gene and the disease.
diabetes (3 papers, 2015 to 2022). "Eleven ST3GAL4 SNPs were significantly associated with the plasma level of VWF antigen before adjustments for age, BMI, hypertension, diabetes, ever-smoking status, and ABO." (PMID 27584569, 2016). "The most significant increased sialyltransferase is St3gal4 (q = 1.14E-26) in diabetes." (PMID 26483702, 2015). "St3gal6 is the most highly expressed α2,3 sialyltransferases in kidney IM; however, St3gal4 is the most significantly changed α2,3 sialyltransferases in diabetes, and may be responsible for the increased UT-A1 sialylation." (PMID 26483702, 2015).
colorectal cancer (2 papers, 2015 to 2024). A primary or metastatic malignant neoplasm that affects the colon or rectum. "Similarly, the increased expression of ST3GAL4 and FUT4 was reported in colorectal carcinomas." (PMID 25923697, 2015).
cutaneous melanoma (2 papers, 2021 to 2024). A primary melanoma arising from atypical melanocytes in the skin. "miR-1180-3p has been reported involving in the regulation of C11of54 in hepatocellular carcinoma and ST3GAL4 in cutaneous melanoma." (PMID 34723759, 2021).
dyslipidemia (2 papers, 2014 to 2022). "Interestingly, ST3GAL4 has been correlated to endothelial dysfunction and the synthesis of E-selectin ligands, which were associated with metabolic syndrome and coronary artery calcification." (PMID 25086711, 2014).
glioma (2 papers, 2015 to 2023). A benign or malignant brain and spinal cord tumor that arises from glial cells (astrocytes, oligodendrocytes, ependymal cells). "Analysis of the primary glioma data showed that members of the ST3GAL family, specifically ST3GAL2 and ST3GAL4, exhibited higher levels of expression." (PMID 38067186, 2023).
influenza (2 papers, 2021). An acute viral infection of the respiratory tract, occurring in isolated cases, in epidemics, or in pandemics; it is caused by serologically different strains of viruses (influenzaviruses) designated A, B, and C, has a 3-day incubation period, and usually lasts for 3 to 10 days. "Meanwhile, the increase in DPP4 (MERS-CoV), ST3GAL4, and ST6GAL1 (influenza) was associated with increased goblet and basal activated cells." (PMID 34198852, 2021).
osteoarthritis (2 papers, 2022 to 2023). A noninflammatory degenerative joint disease occurring chiefly in older persons, characterized by degeneration of the articular cartilage, hypertrophy of bone at the margins and changes in the synovial membrane. "ST3GAL4 is associated with the pathogenesis of osteoarthritis (OA) and LDL-C level." (PMID 34991478, 2022). "Increased ST3GAL4 expression responding to the NF-κB pathway resulted in sialylated CD44 expression, exacerbating osteoarthritis in a mouse model." (PMID 37398192, 2023).
osteosarcoma (2 papers, 2022 to 2024). A usually aggressive malignant bone-forming mesenchymal neoplasm, predominantly affecting adolescents and young adults. "Mechanistically, ST3GAL4 was also associated with cell cycle and mismatch repair, further suggesting that ST3GAL4 influences the development of osteosarcoma." (PMID 38212768, 2024). "In addition, an MRGs-based risk model was constructed and the role of a key risk gene, ST3GAL4, in osteosarcoma cells was explored using molecular biological experiments." (PMID 38212768, 2024). "ST3GAL4 was also associated with the immune response in osteosarcoma and may be an important regulator of the TIME of osteosarcoma." (PMID 38212768, 2024). "Subsequently, ST3GAL4 was found to not only have a high positive coefficient in the risk model, but also to be predominantly expressed in malignant cells (osteoblastic and chondroblastic osteosarcoma cells) compared to other core MRGs." (PMID 38212768, 2024). "Knockdown of ST3GAL4 significantly inhibited proliferation, migration, invasion and glycolysis of osteosarcoma cells and inhibited the M2 polarization of macrophages." (PMID 38212768, 2024). "Flow cytometry analysis further confirmed a lower proportion of M2 macrophages in the ST3GAL4 knockdown group compared to the control group, confirming the regulation of ST3GAL4 on macrophage polarization in osteosarcoma." (PMID 38212768, 2024). "Further, osteosarcoma patients with high ST3GAL4 were found to have significantly worse OS and RFS (all p < 0.001)." (PMID 38212768, 2024). "As expected, the knock down of ST3GAL4 reduced the basal glycolysis level and maximal glycolysis level in osteosarcoma cells." (PMID 38212768, 2024). "We knocked down and overexpressed ST3GAL4 in the osteosarcoma cell lines MG-63 and U2OS to explore its effect on the malignant phenotype of osteosarcoma cells." (PMID 38212768, 2024). "In summary, only ST3GAL4 in the ST3GAL family is associated with both the prognosis and immune characteristics of osteosarcoma." (PMID 38212768, 2024). "This study confirmed the regulatory effect of ST3GAL4 on macrophage polarization in osteosarcoma using a co-culture system." (PMID 38212768, 2024). "There are few studies on the relationship between ST3GAL4 and osteosarcoma hypoxia and osteosarcoma immunity." (PMID 35102149, 2022). "The risk heat map showed that the gene expression of ST3GAL4, TRIM8, STC2, TRPS1, and FAM207A increased from low-risk to high-risk groups, indicating that the five genes in this study were related to osteosarcoma." (PMID 35102149, 2022). "ST3GAL4, TRIM8, STC2, TRPS1, and FAM207A are high-risk genes that are involved in the occurrence and development of osteosarcoma." (PMID 35102149, 2022). "However, further investigation is required to further elucidate the role of ST3GAL4 in the TIME of osteosarcoma." (PMID 38212768, 2024). "In addition, the effects and mechanisms of vitamin & cofactor metabolism and ST3GAL4 on the TIME of osteosarcoma require further in-depth in vivo and in vitro studies." (PMID 38212768, 2024). "In addition, survival analysis showed that only ST3GAL1 was associated with shorter OS and RFS in osteosarcoma, but its prognostic value was not as significant as ST3GAL4." (PMID 38212768, 2024). "Additionally, the hyperactivation of glycolysis in tumors sustains and promotes various malignant behaviors in osteosarcoma cells, which may also be a potential mechanism by which ST3GAL4 influences the malignant phenotype of osteosarcoma cells." (PMID 38212768, 2024). "ST3GAL4 plays a critical role in the progression, glycolysis, and TIME of osteosarcoma and affects the prognosis." (PMID 38212768, 2024). "The present study demonstrated for the first time that knockdown of ST3GAL4 in cell lines (MG-63 and U2OS) suppressed the malignant phenotype of osteosarcoma." (PMID 38212768, 2024).
osteosarcoma (continued). "We performed qRT-PCR to detect the expression of ST3GAL4, TRIM8, STC2, TRPS1, and FAM207A genes in normal human osteoblasts (hFOB1.19) and osteosarcoma cells (MG63 and SJSA-1)." (PMID 35102149, 2022). "The results showed that the expression levels of ST3GAL4, TRIM8, STC2, TRPS1, and FAM207A genes were significantly higher in the osteosarcoma cell line compared to that in the normal human osteoblasts." (PMID 35102149, 2022). "ST3GAL4 plays a critical role in the progression, glycolysis, and TIME of osteosarcoma cells." (PMID 38212768, 2024). "Our findings suggested that ST3GAL4, TRIM8, STC2, TRPS1, and FAM207A could be used as potential biomarkers for the prognosis of patients with osteosarcoma." (PMID 35102149, 2022). "Therefore, we suggested that ST3GAL4, TRIM8, STC2, and FAM207A genes could regulate the immune microenvironment of osteosarcoma by influencing cytokines to promote tumor growth and invasion." (PMID 35102149, 2022). "Notably, the violin plot showed that ST3GAL4, rather than other MRGs, was specifically highly expressed in proliferating osteoblastic osteosarcoma cells, suggesting the potentially important role of ST3GAL4 in the proliferation of osteosarcoma cells." (PMID 38212768, 2024).
type 2 diabetes (2 papers, 2014 to 2025). "Variants in the ST3GAL4 gene have been associated with an increased risk of cirrhosis, type 2 diabetes, and CVD, likely by affecting liver enzyme concentrations." (PMID 40076958, 2025). "Firstly, ST3GAL4 encodes a member of the glycosyltransferase 29 family which was associated with increasing risk of type 2 diabetes and cardiovascular disease." (PMID 25086711, 2014). "The products of ST3GAL4 were associated with increasing risk of cirrhosis, type 2 diabetes and cardiovascular disease by influencing liver enzyme concentrations." (PMID 25086711, 2014).
anxiety-depression (1 paper, 2022). "Using this method, we previously profiled urinary VOCs in a mouse model of TLE induced by amygdala stimulation, and in a mouse model of anxiety-depression produced by a deficiency of sialyltransferase St3gal4." (PMID 37861875, 2022).
avian influenza (1 paper, 2021). Infection of domestic and wild fowl and other birds with influenza A virus. "Therefore, we compared the effects of CMAS or ST3GAL4 knockout on avian influenza and swine influenza." (PMID 34200006, 2021).
Brain atrophy (1 paper, 2024). Partial or complete wasting (loss) of brain tissue that was once present. "One of the shared DamAge glia-clock CpGs mapped to the promoter of ST3GAL4, a gene associated with brain atrophy in AD patients and that correlates with Braak staging." (PMID 39760516, 2024).
chronic myeloid leukemia (1 paper, 2018). "Elevated ST3Gal4 in chronic myeloid leukemia (CML) cells is associated with imatinib resistance." (PMID 30237983, 2018).
lung carcinoma (1 paper, 2016). "Moreover, the expression of this specific ST3GAL4 mRNA is increased by TNF treatment in both the human bronchial mucosa and in A549 lung cancer cell line, and is correlated with sLex and 6-sulfo-sLex over-expression on glycoproteins." (PMID 27916834, 2016).
meningioma (1 paper, 2024). A generally slow growing tumor attached to the dura mater. "In the GEO database, mRNA expression of ST3GAL4 was significantly decreased in grade II and III meningiomas (P < 0.05), while the others (ST3GAL1, ST3GAL3, ST3GAL6, ST6GAL1, and ST6GALNAc1) were not." (PMID 38274327, 2024).
metastatic disease (1 paper, 2016). "The α2-3-sialyltransferases ST3Gal4 and ST3Gal6 are critical to the generation of functional E- and P-selectin ligands and overexpression of these STs have been linked to increased risk of metastatic disease in solid tumors and poor outcome in multiple myeloma." (PMID 27148485, 2016).
mumps (1 paper, 2017). "FUT2 (rs516316, P = 9.63 × 10−72, OR = 1.25) and ST3GAL4 (rs3862630, P = 1.21 × 10−8, OR = 1.13) also have highly significant associations with mumps." (PMID 28928442, 2017).
nematode infection (1 paper, 2013). "The dominant airway goblet cell mucin produced after nematode infection was sialomucin, and this appeared in association with the upregulation of the mucin sialylation factor St3gal4." (PMID 27335862, 2013). "We have previously shown that nematode infection also induced intestinal epithelial responses that were characterised by goblet cell hyperplasia and led to an increase in production of sialomucin, sulfomucin, Muc2, the resistin-like molecule beta (Retnlb), and St3gal4." (PMID 27335862, 2013).
ovarian tumor (1 paper, 2023). "We observed 24 ABH antigen synthesis‐related genes in which five genes (FUT1, FUT2, FUT3, B3GNT3, and B3GNT2) were up‐regulated and three genes (ST3GAL3, ST3GAL4, and B3GALT2) were down‐regulated in ovarian tumor tissue versus adjacent tissues in all samples." (PMID 36415180, 2023).
proliferative diabetic retinopathy (1 paper, 2025). Advanced retinopathy due to diabetes mellitus characterized by the formation of new vessels in the retina. "A study on proliferative diabetic retinopathy (PDR) demonstrated that high-glucose stimulation upregulated the expression of the sialyltransferase ST3GAL4." (PMID 40770702, 2025).
renal carcinoma (1 paper, 2021). A carcinoma arising from the epithelium of the renal parenchyma or the renal pelvis. "The relationship between ST3GAL4 and cancer occurrence had also been widely reported; for example, its expression was reduced in renal cancer cells and it was associated with the malignant development of subsequent cancers." (PMID 34200006, 2021).
thrombocytopaenia (1 paper, 2021). "Supporting the importance of sialyl transferases in the platelets’ lifespan, mice lacking ST3GAL4 (an enzyme that transfers sialic acid onto β1,4-galactose) develop thrombocytopaenia due to increased platelet clearance via the hepatic Ashwell–Morell receptor." (PMID 33924503, 2021).
uterine cancer (1 paper, 2025). Primary or metastatic malignant neoplasm involving the uterine corpus and/or the cervix. "For instance, overexpression of ST3GAL4 has been associated with poor prognosis and disease progression in gastric, pancreatic, cervical, and uterine cancers." (PMID 41445790, 2025).
cancer (30 papers, 2007 to 2026). A tumor composed of atypical neoplastic, often pleomorphic cells that invade other tissues. "The sialyltransferase ST3GAL4 is implicated in individual cancers, but its pan-cancer landscape and systemic associations remain undefined." (PMID 42072307, 2026). "Tumor microenvironment analyses revealed significant associations: ST3GAL4 expression positively correlated with cancer-associated fibroblast and endothelial cell infiltration but was inversely associated with cytotoxic T-cell abundance." (PMID 42072307, 2026). "ST3GAL1 is mainly associated with O-linked sialylation in cancer cells, whereas ST3GAL4 is mainly associated with N-linked sialylation." (PMID 30375371, 2018). "Our in silico survival analysis indicated the poor prognostic significance of increased ST3GAL4 expression in ovarian and lymph node positive TNBC patients, in agreement with the fact, that increase in ST3GAL4 and associated sialylation is associated with cancer progression and chemo-resistance." (PMID 33579350, 2021). "Similarly, ST3GAL4 is also upregulated in cancer, and is associated with poor prognosis; metastasis and the synthesis of Sialyl Lewix X (sLeX) in gastric carcinoma." (PMID 31614918, 2019). "We concluded that CD82 decreases sLea/x expression via the down-regulation of ST3GAL4 expression and thereby reduces the adhesion of cancer cells to blood vessels, which results in inhibition of metastasis." (PMID 25923697, 2015). "Interestingly, recent studies also observed increased ST3GAL4 expression in the stroma in other cancer types, including colorectal, lung, cervical and esophageal cancer." (PMID 38594506, 2024). "Therefore, we conclude that CD82 down-regulates ST3GAL4 and regulates sialyl Lewis antigen-mediated cancer cell adhesion to blood vessels and, thereby, the inhibition of cancer cell metastasis." (PMID 25923697, 2015). "Moreover, it has been described that TNF-α can induce SLex and 6-sulfo-SLex expression in human cancer cells, by increasing the expression of ST3GAL4." (PMID 23799130, 2013). "GOLPH3 has been identified as an oncogenic protein in cancer localized to the Golgi, and in a previous study, we found that its interactions with PI4P and sialyltransferases (ST3Gal4 or ST6Gal1) are essential for the regulation of sialylation." (PMID 37451482, 2023). "Key examples of sialyltransferases important in cancer include ST6GAL1; ST3GAL4 ST3GAL6 and ST6GalNAc1/2." (PMID 31614918, 2019). "Of note, LY6D, ST3GAL4, ASS1, PTP4A3 (also named PRL-3), UBE2C (also named UBCH10), and E2F3 are novel oncogenes and biomarkers whose overexpression are related to metastases, migration, or proliferation of NSCLC and other cancers." (PMID 27935865, 2017).
tumor (30 papers, 2009 to 2026). "ST3GAL4 is involved in the synthesis of Siglec-9 ligands on PDAC tumor cells and is associated with decreased survival." (PMID 38594506, 2024). "ST3GAL4 encodes for β-galactosidase α-2,3-sialyltransferase 4, which is involved in the biosynthesis of tumor antigens and is closely related to the occurrence and progression of cancer." (PMID 35102149, 2022). "ST3GAL4 has also been identified to be associated with sialyl-LewisX expression on endothelial cells, creating a binding site for L-selectin on T cells and mediating extravasation of T cells to home to secondary lymphoid organs or the tumor site." (PMID 40885395, 2025). "Experimental validation included immunofluorescence staining for ST3GAL4 protein in human tumor specimens." (PMID 42072307, 2026). "In PDAC, upregulation of ST3GAL1 and ST3GAL4 in tumor cells was identified as the main contributor to the synthesis of Siglec-7 and Siglec-9 ligands." (PMID 40885395, 2025). "A recent investigation revealed that ST3GAL4 not only contributes to protein glycosylation but also influences the Siglec-7 and Siglec-9 signaling pathways by facilitating ligand synthesis in tumor cells, subsequently promoting macrophage polarization." (PMID 40534850, 2025). "Samples with high expression of ST3GAL4 also had lower ImmuneScore, StromalScore and higher tumor purity." (PMID 38212768, 2024). "Using multiplex immunohistochemistry and transcriptomics, we show that PDAC stroma is enriched in sialic acid-containing glycans compared to tumor cells and normal fibroblasts, and characterized by ST3GAL4 expression." (PMID 38594506, 2024). "The protein expression of ST3GAL4 was found to be significantly higher in tumor tissue than in normal tissue." (PMID 38212768, 2024). "ST3GAL4 is involved in generation of the sialyl Lewis X antigen, often upregulated in tumor cells to facilitate invasion, and is described to generate the ligands for Siglec-936,51." (PMID 38594506, 2024). "Our results demonstrate elevated sialic acid levels in CAFs compared to tumor cells, with ST3GAL4 identified as the key regulatory enzyme in CAF sialylation." (PMID 38594506, 2024). "SETD1A knockdown changed the landscape of SEs, resulting in activation of the transcription of SE-driven tumor suppressors, such as ST3GAL4, AKAP12, PTPN1, AQP9, and ANKRD11." (PMID 37581938, 2023). "The interplay between the different sialyltransferases known to add NeuAc residues onto N-glycans, such as ST6GAL1 or the ST3GAL4/5/6, clearly plays a major role in this context of the tumour microenvironment." (PMID 36289103, 2022). "We identified the expression of the α2,3 sialyltransferases ST3GAL1 and ST3GAL4 as main contributor to the synthesis of ligands for Siglec-7 and Siglec-9 in tumour cells." (PMID 33627655, 2021). "A recent study has shown that ST3GAL4 is not only involved in protein glycosylation processes, but also affects the signaling pathways of Siglec-7 and Siglec-9 by promoting the synthesis of ligands in tumor cells, thereby promoting macrophage polarization." (PMID 38212768, 2024). "In addition, ST3GAL4 is related to an increased invasive phenotype in tumor cells as it generates the glycan sialyl-Lewis X, which facilitates cell adhesion." (PMID 38594506, 2024). "In addition, the upregulation of ST3GAL4 was also reported to activate the c-Met signaling pathway and accelerate tumor cell invasion." (PMID 33524390, 2021). "Several of the GRGs and GRPs commonly correlated with survival in different tumor types are actually associated with specific cells in the stromal compartment (as MFNG in all immune cells, LGALS2 in myeloid cells, ST6GAL1 in B and plasma cells and CHPF and ST3GAL4 for fibroblasts)." (PMID 38384845, 2024). "Focusing on glycosyltransferases expression in tumor tissues, we observed two distinct expression clusters, segregating FUT3, FUT4, FUT6, and ST3GAL4 transcripts, from FUT7, FUT9, ST3GAL3, and ST3GAL6." (PMID 39508360, 2025).